MSI2 (musashi RNA binding protein 2)
Diseases named in the same sentence as MSI2 in open-access papers (continued):
Sharing a sentence is not in itself a finding about the gene and the disease.
neuroblastoma (5 papers, 2017 to 2025). Neuroblastoma (NB) is the most common solid, extracranial childhood tumor. "RT‐PCR, immunoblot and Alamar blue assays showed that forced PRKCQ‐AS1 overexpression resulted in BMX mRNA and protein up‐regulation, ERK protein phosphorylation and neuroblastoma cell proliferation, and MSI2 or BMX knockdown largely blocked the effects." (PMID 40103284, 2025). "The knockdown of MSI2 decreases the proliferation and colony formation and increases apoptosis in human neuroblastoma cell lines." (PMID 41189817, 2025). "Taken together, our data suggests that high levels of PRKCQ‐AS1 and MSI2 expression in tumor tissues independently predict poor prognosis in neuroblastoma patients." (PMID 40103284, 2025). "In the current study, we found that HuD interacts with Msi2 transcript and positively regulates it in the mouse neuroblastoma (N2a) cells." (PMID 39680531, 2024). "Furthermore, a recent study indicated that MSI2, a gene related to the malignant property of neuroblastoma cells, upregulated G6PD and enhanced PPP." (PMID 41291487, 2025). "Importantly, while PRKCQ‐AS1 or MSI2 overexpression augments MYCN nonamplified neuroblastoma cell proliferation, MSI2 knockdown reverses PRKCQ‐AS1‐induced neuroblastoma cell proliferation, and PRKCQ‐AS1 knockdown blocks MSI2‐mediated neuroblastoma cell proliferation." (PMID 40103284, 2025). "To determine if Msi2 undergoes regulatory phosphorylation in mammalian cells, we assessed Msi2 phosphorylation status during the transition from proliferation to differentiation using an immortalized murine myeloblast-like cell line, 32D as well as a human neuroblastoma cell line (SHSY5Y)." (PMID 28912529, 2017). "The study demonstrates that PRKCQ‐AS1 RNA interacts with MSI2 protein to induce neuroblastoma tumorigenesis, and that targeting PRKCQ‐AS1 and MSI2 interaction with small molecule compounds is an effective anticancer strategy." (PMID 40103284, 2025). "In human neuroblastoma tissues, high levels of PRKCQ‐AS1 and MSI2 expression correlate with poor patient outcomes, independent of current prognostic markers." (PMID 40103284, 2025). "PRKCQ‐AS1 RNA interacts with MSI2 protein, resulting in the stabilization and overexpression of oncogenic mRNAs including BMX, ERK protein phosphorylation and neuroblastoma cell proliferation in vitro and tumor progression in vivo." (PMID 40103284, 2025). "PRKCQ‐AS1 RNA forms a complex with MSI2 protein to induce BMX mRNA stabilization and overexpression, ERK protein phosphorylation and neuroblastoma cell proliferation." (PMID 40103284, 2025). "Taken together, the data suggest that PRKCQ‐AS1 RNA interacts with MSI2 protein to up‐regulate BMX expression and augment ERK protein phosphorylation, leading to neuroblastoma cell proliferation." (PMID 40103284, 2025). "Consistent with data from PRKCQ‐AS1 or MSI2 knockdown, treatment with NSC617570 reduces BMX expression, ERK protein phosphorylation, neuroblastoma cell proliferation and clonogenic capacity." (PMID 40103284, 2025). "Compound NSC617570 blocks PRKCQ‐AS1 binding to MSI2, leading to BMX mRNA disassociation from MSI2 protein, BMX reduction, ERK dephosphorylation, neuroblastoma cell proliferation suppression in vitro and tumor growth inhibition in vivo." (PMID 40103284, 2025). "RT‐PCR, immunoblot and Alamar blue assays showed that forced MSI2 overexpression resulted in BMX mRNA and protein up‐regulation, ERK protein phosphorylation and neuroblastoma cell proliferation, and PRKCQ‐AS1 or BMX knockdown largely blocked the effects." (PMID 40103284, 2025). "Overexpression of PRKCQ‐AS1 or MSI2 enhances BMX expression, ERK protein phosphorylation and neuroblastoma cell proliferation; MSI2 or BMX knockdown blocks the effects of PRKCQ‐AS1 overexpression; and PRKCQ‐AS1 or BMX knockdown blocks the effects of MSI2 overexpression." (PMID 40103284, 2025).
neuroblastoma (continued). "Our findings therefore identify PRKCQ‐AS1 and MSI2 as important novel co‐factors for MYCN nonamplified neuroblastoma tumorigenesis, and provide novel targets and a novel therapeutic agent for the treatment of MYCN nonamplified neuroblastoma." (PMID 40103284, 2025). "We next examined the role of MSI2 and BMX in neuroblastoma cell proliferation." (PMID 40103284, 2025). "AlphaScreen of a compound library identifies NSC617570 as an efficient inhibitor of PRKCQ‐AS1 RNA and MSI2 protein interaction, and NSC617570 reduces BMX expression, ERK protein phosphorylation, neuroblastoma cell proliferation in vitro and tumor progression in mice." (PMID 40103284, 2025). "We observed a similar regulatory phosphorylation of mammalian Msi2 when ectopically expressed in Xenopus oocytes, as well as the endogenous mammalian Msi2 in murine 32D myoblastic cells and human SH-SY5Y neuroblastoma cells in response to extracellular signals that induce cell differentiation." (PMID 28912529, 2017). "By contrast, using the median, low or upper quartile of PRKCQ‐AS1, MSI2 and BMX RNA expression as the cut‐off, Kaplan‐Meier survival analyses showed that high levels of PRKCQ‐AS1, MSI2 or BMX expression in MYCN‐amplified human neuroblastoma tissues did not correlate with poor patient prognosis." (PMID 40103284, 2025). "In addition, high levels of PRKCQ‐AS1 and MSI2 expression in human neuroblastoma tissues predict poor patient survival rates, independent of current prognostic markers." (PMID 40103284, 2025). "We observed a low level basal S303 phosphorylation of Msi2 in proliferating human SHSY5Y neuroblastoma cells grown in non-adherent spheroid culture and an increase in Msi2 regulatory phosphorylation in response to retinoic acid induced differentiation of SHSY5Y cells." (PMID 28912529, 2017). "In human neuroblastoma tissues, high levels of PRKCQ‐AS1, MSI2 or BMX expression predict poor prognosis in MYCN nonamplified but not MYCN‐amplified patients." (PMID 40103284, 2025). "PRKCQ‐AS1 or MSI2 knockdown reduces, while its overexpression enhances, BMX mRNA stability and expression, ERK protein phosphorylation and MYCN nonamplified neuroblastoma cell proliferation." (PMID 40103284, 2025). "In addition, we have identified a small molecule compound inhibitor of the PRKCQ‐AS1 RNA and MSI2 protein interaction and have confirmed its anticancer efficacy in vitro and in a mouse model of MYCN nonamplified neuroblastoma." (PMID 40103284, 2025). "Taken together, the data demonstrate that PRKCQ‐AS1 interacts with MSI2 to enhance BMX expression, resulting in ERK protein phosphorylation and MYCN nonamplified neuroblastoma tumorigenesis, and that PRKCQ‐AS1 and MSI2 interaction is a valid therapeutic target." (PMID 40103284, 2025).
thyroid cancer (5 papers, 2014 to 2021). "The MSI-2 mRNA expression was highly overexpressed in a variety of cancer types, including cervical, breast, head and neck, kidney papillary, lung, sarcoma, skin melanoma, and thyroid cancer as compared to the corresponding normal tissues." (PMID 29073938, 2017). "No increased expression of Msi2 or Msi2 variant 2 was observed in prostate adenocarcinoma, thyroid carcinoma or kidney renal clear cell carcinoma when compared to normal adjacent tissue." (PMID 28912529, 2017).
colitis (4 papers, 2017 to 2024). Inflammation of the colon. "Thus, mice with conditional MSI2 knockout in ILC3s were used to construct a DSS-induced colitis model and explore its effects on the pathogenesis of IBD and the species, quantity and function of the intestinal microbiota." (PMID 36713428, 2022). "In summary, the deletion of MSI2 in ILC3s can attenuate DSS-induced colonic inflammation in mice by affecting the diversity, composition and function of the intestinal microbiota, and Lactobacillaceae among the Firmicutes could play an important role in this process." (PMID 36713428, 2022). "Our previous studies identified that MSI2 is involved in metabolic reprogramming-mediated immune infiltration in ccRCC and immune dysregulation in DSS-induced colitis." (PMID 38347600, 2024). "To investigate the effect of MSI2 deletion in ILC3s, we analyzed the quantities of ILC3s in the mouse colon by constructing a DSS-induced colitis model." (PMID 36713428, 2022).
lung adenocarcinoma (4 papers, 2020 to 2025). A carcinoma that arises from the lung and is characterized by the presence of malignant glandular epithelial cells. "Principal component analysis shows a clear separation between the control and Msi2-knockdown cells and significant changes in over ~170 genes, highlighting the marked impact that loss of Msi2 has on the transcriptional profile of lung adenocarcinoma." (PMID 40047406, 2025). "Our finding that the loss of Msi2 prior to transformation significantly impacts tumor initiation prompts the interesting question of whether Msi2 signaling can influence early tumor growth for lung adenocarcinoma." (PMID 40047406, 2025). "Msi2 has been reported to be overexpressed in human lung adenocarcinoma and regional metastases, and its inhibition in human cell lines has been shown to reduce invasive and metastatic potential in vitro." (PMID 40047406, 2025). "Here, we have utilized a combination of genetic models and patient-derived xenografts (PDXs) to determine the role of Msi2 signaling in the growth and progression of lung adenocarcinoma." (PMID 40047406, 2025). "Inhibition of Msi2 in PDXs also led to impaired tumor growth in vivo, suggesting that dependence on Msi2 is conserved in human lung adenocarcinoma." (PMID 40047406, 2025). "This work also led to the identification of several novel effectors of lung adenocarcinoma regulated by Msi2." (PMID 40047406, 2025). "The findings presented here identify a novel role for Msi2 in the growth and progression of lung adenocarcinoma and suggest that this role extends to human disease." (PMID 40047406, 2025). "Taken together these results suggest that Msi2 not only marks cells with an enhanced capacity for tumor growth but is also required for initiation and progression of lung adenocarcinoma." (PMID 40047406, 2025). "Collectively, these findings reveal a critical role for Msi2 in aggressive lung adenocarcinoma, lend new insight into the biology of this disease, and identify potential new therapeutic targets." (PMID 40047406, 2025). "Mechanistically, Msi2 triggered a broad range of pathways critical for tumor growth, including several novel effectors of lung adenocarcinoma." (PMID 40047406, 2025). "Here, we have used genetically engineered and autochthonous models to show that Msi2 is critically required in the development and progression of primary lung adenocarcinoma." (PMID 40047406, 2025). "We conclude that the MSI2/VEGFR2 axis contributes to lung adenocarcinoma progression and is worth further investigations and therapeutic targeting." (PMID 37173995, 2023). "Since MSI2 directly binds VEGFR2 mRNA in human lung adenocarcinoma cell lines, we established cell lines with MSI2 depletion and overexpression to evaluate the effect of MSI2 expression on VEGFR2 and VEGF-A protein levels." (PMID 37173995, 2023). "Next, we validated VEGFR2 protein regulation by MSI2 in several human lung adenocarcinoma cell line models." (PMID 37173995, 2023). "Taken together, we conclude that MSI2 directly regulates VEGFR2 mRNA translation in human lung adenocarcinoma." (PMID 37173995, 2023). "ETV4 promotes proliferation and invasion of lung adenocarcinoma by transcriptionally upregulating MSI2." (PMID 31992202, 2020). "Msi2-expressing cells preferentially favor tumor growth in lung adenocarcinoma." (PMID 40047406, 2025). "Furthermore, these findings identify novel effectors of lung adenocarcinoma regulated by Msi2 thereby lending new insight into the mechanism by which Msi2 exerts its influence on this disease." (PMID 40047406, 2025). "Finally, using RNA-sequencing (RNAseq) analysis we show that Msi2 can trigger a range of pathways critical for tumor growth, including several new effectors of lung adenocarcinoma." (PMID 40047406, 2025).
lung adenocarcinoma (continued). "We found that MSI2 depletion leads to a strong decrease in VEGFR2 protein levels in murine and human lung adenocarcinoma cell lines." (PMID 37173995, 2023). "As MSI2 regulates VEGFR2 protein levels, we evaluated cell proliferation along with VEGFR2 downstream signaling in human lung adenocarcinoma cell lines upon MSI2 depletion." (PMID 37173995, 2023). "MSI2 protein directly regulates VEGFR2 and PTEN protein levels via VEGFR2 and PTEN mRNA binding in lung adenocarcinoma." (PMID 37173995, 2023). "Finally, MSI2 expression positively correlated with VEGFR2 and VEGF-A protein levels in human lung adenocarcinoma samples." (PMID 37173995, 2023). "This suggests that MSI2 may directly regulate PTEN mRNA levels and affect AKT signaling in lung adenocarcinoma." (PMID 37173995, 2023).
medulloblastoma (4 papers, 2013 to 2021). A malignant, invasive embryonal neoplasm arising from the cerebellum. "In medulloblastoma, MSI2 is a typical SOX2-associated protein." (PMID 27092875, 2017). "Together, our studies identify a large set of SOX2-associated proteins in DAOY medulloblastoma cells and identify two proteins, MSI2 and USP9X, that warrant further investigation to determine whether they are potential therapeutic targets for brain cancer." (PMID 23667531, 2013). "Only one study in medulloblastoma shows that MSI2 knockdown significantly up-regulates Numb protein in DAOY MB cells." (PMID 27092875, 2017). "In the particular case of medulloblastoma, Msi1 and Msi2 show very distinctive expression patterns in MB subgroups and high Msi2 expression does not show any impact on disease prognosis." (PMID 35011618, 2021).
amyotrophic lateral sclerosis (3 papers, 2020 to 2021). Amyotrophic lateral sclerosis (ALS) is a neurodegenerative disease characterized by progressive muscular paralysis reflecting degeneration of motor neurons in the primary motor cortex, corticospinal tracts, brainstem and spinal cord. "Here, we investigated the expression and cellular localization of MSI1 and MSI2 in the brains tissues of Alzheimer’s disease (AD), amyotrophic lateral sclerosis (ALS) and frontotemporal dementia (FTD) as well as in the wild-type mice and tau knock-out and P301L tau mouse models." (PMID 32855391, 2020).
glioma (3 papers, 2021 to 2026). A benign or malignant brain and spinal cord tumor that arises from glial cells (astrocytes, oligodendrocytes, ependymal cells). "Western blot was utilized to explore the expression level of MSI2 protein in normal brain tissues (NBTs), glioma tissues, NHAs, and the GBM cell lines U251 and U373." (PMID 34047477, 2021). "In the present study, a significant increase in MSI2 expression was detected in glioma tissues and GBM cells." (PMID 34047477, 2021). "Immunohistochemical staining showed that MSI2 was mainly expressed in the nucleus of glioma tumor cells and that its expression increased with increasing pathological grade." (PMID 34047477, 2021). "Further, mice injected with a combination of the three showed minimal xenograft glioma volume and the longest survival time compared with those in the MSI2 knockdown, SNORD12B knockdown, or ZBTB4 overexpression group." (PMID 34047477, 2021). "Compared with that in NBTs, the MSI2 protein level in glioma tissues was higher and was increased at higher pathological grades." (PMID 34047477, 2021). "The expression of MSI2 in glioma was elevated based on data obtained from the Cancer Genome Atlas." (PMID 34047477, 2021). "Finally, our in vivo study revealed that MSI2 knockdown, SNORD12B knockdown, or ZBTB4 overexpression suppressed xenograft glioma tumor growth and was associated with prolonged survival." (PMID 34047477, 2021). "The present study revealed the oncogenic nature of MSI2 and SNORD12B and the antioncogenic role of ZBTB4 in glioma." (PMID 34047477, 2021). "MSI2 and SNORD12B expression was significantly increased and ZBTB4 expression was decreased in glioma tissues and cells." (PMID 34047477, 2021). "Thus, the MSI2/SNORD12B/FIP1L1/ZBTB4 positive feedback loop plays a crucial role in regulating the glycolipid metabolism of GBM cells and provides a potential drug target for glioma treatment." (PMID 34047477, 2021). "In this study, we identified elevated expression of Musashi RNA-binding protein 2 (MSI2) and Long intergenic nonprotein coding RNA 667 (LINC00667) in glioma co-cultured endothelial cells." (PMID 41581866, 2026).
lymphoma (3 papers, 2021 to 2022). A malignant (clonal) proliferation of B- lymphocytes or T- lymphocytes which involves the lymph nodes, bone marrow and/or extranodal sites. "We observed that MSI2 depletion reduced about 50% tumor growth and resistant tumor cells escaped due to inefficient MSI2 knockdown in a lymphoma xenograft model." (PMID 36167829, 2022). "The lymphoma cells resistant to the PRMT5 inhibitor were those that evaded successful MSI2 shRNA-mediated knockdown." (PMID 36167829, 2022). "In summary, our study provides data for the role of the PRMT5/MSI2 axis in regulating the key lymphoma drivers, c-MYC and BCL-2." (PMID 36167829, 2022). "In the most aggressive forms of lymphoma, MSI2 is overexpressed and cooperates with PRMT5 in maintaining c-MYC and BCL-2, which confers resistance to PRMT5 inhibition." (PMID 36167829, 2022). "Additionally, shRNA-mediated depletion of MSI2 modestly decreased lymphoma cell proliferation in two GSK591-sensitive cell lines, Z-138 and OCI-LY19, but resulted in a 10-fold decrease in the IC50 of GSK-591." (PMID 36167829, 2022). "Considering this, it would be interesting to conduct studies on B-cell lymphoma mouse models to determine whether MSI2 is required for both lymphoma initiation and progression." (PMID 36167829, 2022). "PRMT5 expression correlates with MSI2 expression in lymphoma patients." (PMID 36167829, 2022). "Thus, we propose a therapeutic strategy in lymphoma that combines PRMT5 with MSI2 or BCL-2 inhibition." (PMID 36167829, 2022). "Moreover, more than 2% of ~ 5000 samples from patients with haematopoietic and lymphoid cancers included in the COSMIC Release v94 database carried coding mutations in MYO9A, PALM2-AKAP2, MSI2 or CACNA1E (range 121–202 mutated samples per gene)." (PMID 34362951, 2021). "Therefore, to inhibit the PRMT5/MSI2/c-MYC/BCL-2 axis we proposed two drug combination strategies; the first one consists of targeting PRMT5 in combination with a MSI2 inhibitor, which results in loss of c-MYC and BCL-2 translation cell-cycle regulators in lymphoma cells." (PMID 36167829, 2022). "We examined the expression of MSI2 across different DLBCL subtypes ABC, GCB, and other non-characterized subtypes from the BC Cancer Lymphoid Cancer Dataset (n = 322)." (PMID 36167829, 2022). "Furthermore, MSI2 and PRMT5 protein abundance are lower in non-malignant B cells and de novo MCL and DLBCL primary samples compared to relapsed MCL, relapsed DLBCL, and lymphoma cell lines." (PMID 36167829, 2022).
myeloid malignancies (3 papers, 2020 to 2026). "Here, we identified a noncoding regulatory variant, rs17834140-T, that protects against CH and myeloid malignancies by selectively down-regulating the RNA-binding protein MSI2 in HSCs." (PMID 41477881, 2026). "In myeloid malignancies, HOXA9 upregulates MSI2, and MSI2 then downregulates NUMB, a negative regulator of NOTCH, thereby promoting cell division during blast crisis." (PMID 33504942, 2021).